NUDT21 (nudix hydrolase 21)
Diseases named in the same sentence as NUDT21 in open-access papers (continued):
Sharing a sentence is not in itself a finding about the gene and the disease.
tumor (continued). "RNA modification writers, e.g., NUDT21, can switch APA sites in genes regulating the cell cycle, apoptosis, and metabolism, resulting in the inhibition of tumor cell proliferation, metastasis, and tumorigenesis." (PMID 33557837, 2021). "For example, in bladder cancer (BC), NUDT21 regulates the expression of ANXA2 and LIMK2 in the Wnt/β-catenin and NF-κB signaling pathways and inhibits tumor progression." (PMID 33526057, 2021). "To confirm this result, we examined NUDT21 expression using quantitative real-time reverse transcription polymerase chain reaction (RT-qPCR) in 15 pairs of GBM tissues and corresponding non-tumor tissues." (PMID 29311812, 2017). "Genetic ablation of NUDT21 impairs CRC cell proliferation and triggers CD8+ T cell anti-tumor response through disrupting cholesterol biosynthesis, leading to delayed tumor progression in syngeneic mouse models." (PMID 41255211, 2025). "The combined results showed that NUDT21 was extremely expressed and had a poor prognosis in LUAD, PAAD, HNSC and THCA, while it had a better prognosis in CHOL, COAD, GBM, and KIRC, demonstrating the heterogeneity of NUDT21 expression in different tumor type." (PMID 38349866, 2024). "Subsequently, employing bioinformatics pan-cancer analysis and conducting functional experiments on HHNSCC cells, we discovered that NUDT21 functions as an oncogene in HHNSCC, promoting cancer cell proliferation, suppressing apoptosis, and playing a crucial role in the tumor microenvironment." (PMID 38349866, 2024). "The analysis further indicated that three m6A readers are differentially expressed in the mCRPC tissues, where the YTHDF2 gene showed significant upregulation, while the NUDT21 and SRSF10 genes showed significant downregulation in mCRPC compared to both the localized tumor and normal tissues." (PMID 38610981, 2024). "Scatter plots revealed that CLP1, CPSF2, and NUDT21 expressed significantly higher in tumor tissues than in normal gastric tissues, which was completely consistent with the results of the TCGA database." (PMID 36874129, 2023). "We also compared Nudt21 content in POL and OL cells that differ in metastatic colonization efficiency and we found that NUDT21 expression was significantly lower in POL cells, consistent with the reported tumor‐suppressor function of Nudt21." (PMID 37356089, 2023). "Although NUDT21 was previously found as a tumor suppressor in some types of cancer, no NUDT21-favoring therapy has been developed, possibly due to the challenge in elevating the level of therapeutic protein." (PMID 37737260, 2023). "The lack of understanding of the mechanisms and regulation of APA, miRNA and their interaction and roles has underscored the need for further research regarding their role in cancer and other diseases.This paper will describe the impact on tumor from the relationship between miRNA, APA and NUDT21." (PMID 36816917, 2023). "Functional studies of the genes composing the APA machinery have highlighted their relevance to tumor growth; for example, in glioblastoma, overexpression of the APA factor NUDT21 (a repressor of proximal 3′-UTR PAS usage) reduces tumor cell proliferation and inhibits tumor growth in vivo." (PMID 32029502, 2020). "Besides, the expression of NUDT21 mRNA was significantly higher in tumor tissues than in non-tumor tissues." (PMID 38349866, 2024). "In addition, related literature found that NUDT21 recognizes tumor cell proliferation and immune cell infiltration of TME through events with APA, and this TME infiltration leads to the activation of NUDT21, which induces a different transcriptional program to address these changes." (PMID 38349866, 2024).
cancer (32 papers, 2017 to 2026). A tumor composed of atypical neoplastic, often pleomorphic cells that invade other tissues. "We also examined the interaction between NUDT21 promoter methylation and cancer subtypes, CTL risk and TIDE." (PMID 38349866, 2024). "Cancers in which NUDT21 was inversely associated with immune levels were also inversely associated with most immune checkpoints, including LUSC, THYM, TGCT, and TARGET-NB." (PMID 38349866, 2024). "We also noted that hyperinflation of the NUDT21 promoter is positively associated with most immunostimulants, suggesting that NUDT21 expression affects chemokine-mediated immunostimulation of cancer." (PMID 38349866, 2024). "The histograms showed that NUDT21 was significantly associated with 10 cancer immune subtypes." (PMID 38349866, 2024). "Notably, in HNSCC cancers, elevated expression of NUDT21 was significantly associated with poor prognosis." (PMID 38349866, 2024). "Therefore, in this study, we aimed to investigate the diagnostic efficacy and prognostic value of NUDT21 in cancer through comprehensive analysis tools." (PMID 38349866, 2024). "However, we noted that in numerous cancers, some markers were positively associated with NUDT21." (PMID 38349866, 2024). "NUDT21 knockdown not only inhibits cell growth but also reduces malignancy traits like anchorage-independent growth and cancer stemness." (PMID 42086673, 2026). "On the other hand, APA-regulatory proteins, such as Nudix Hydrolase 21 (NUDT21) and heterogeneous nuclear ribonucleoproteins C (hnRNPC), play important roles in cancer." (PMID 40483535, 2025). "To study the functional roles of NUDT21 and its interacting or co-expressed genes in cancer, we performed a sequential functional enrichment analysis." (PMID 38349866, 2024). "In our study, we first systematically described the differential expression of NUDT21 and its prognostic value in pan-cancer analysis through bioinformatics research." (PMID 38349866, 2024). "As confirmed by IHC staining and average optical density measurement, NUDT21 was significantly expressed in cancer tissues compared to adjacent tissues in HHNSCC." (PMID 38349866, 2024). "Based on immunosuppressive score, we found that NUDT21 plays an essential role in the immunosuppressive environment by suppressing immune checkpointing effect in most cancers." (PMID 38349866, 2024). "According to the UALCAN results, NUDT21 protein expression was upregulated in cancers of OV, BRCA, COAD, LUAD, LIHC, HNSC, UCEC, and GBM." (PMID 38349866, 2024). "Nine major cancer subtypes positively associated with CTLs; In HNSC, CHOL and MESO, ESCA, NUDT21 promoter methylation was positively correlated with CTL infiltration." (PMID 38349866, 2024). "Their strong positive correlation in cancer suggests that in most cancers, elevated NUDT21 promotes methylation of target gene promoters and represses their expression." (PMID 38349866, 2024). "The prognosis of NUDT21 in pan-cancer and its role in the immune microenvironment were investigated by different online databases." (PMID 38349866, 2024). "Pan-cancer-based analysis provides insight into the function of NUDT21 in the tumorigenesis of different cancers as well as providing a pre-study basis for the study of some cancers." (PMID 38349866, 2024). "The violin diagram showed that the main 6 cancers increased expression of NUDT21 in C4 subtypes of LGG, STAD, LUSC, and KIRC, suggesting that a negative correlation with lymphocyte function." (PMID 38349866, 2024). "In certain cancers, NUDT21 upregulation was correlated with increased infiltration of immune cells such as M2 macrophages." (PMID 38349866, 2024). "NUDT21 has emerged as an important regulator of cell fate decisions in normal and pathological conditions, but its involvement in cancer is not fully understood." (PMID 38195952, 2024).
cancer (continued). "Surprisingly, we found that elevated expression of NUDT21 correlated with RNA regulatory genes in numerous cancers, including numerous cancers gm1A, m5C and m6a, suggesting that NUDT21 is also involved in RNA modification." (PMID 38349866, 2024). "From multiple perspectives, these results suggest that NUDT21 is involved in creating an immunosuppressive environment in many cancers, probably through the inhibition of immunoregulatory functions and immune checkpoint effects." (PMID 38349866, 2024). "Due to the lack of current knowledge regarding the mechanisms of action and regulation of NUDT21 and alternative polyadenylation, it is necessary to further examine their role in cancer as well as in other diseases." (PMID 36816917, 2023). "Our data reveal a novel link between NUDT21 and signaling pathways during cancer development and progression." (PMID 31695759, 2019). "In addition, we performed analyses of MSI, TMB, neoantigens and ploidy correlations with NUDT21, as these genomic alterations are commonly seen in cancer and affect patient prognosis and treatment response." (PMID 38349866, 2024). "Thus, NUDT21 plays an important role in creating an immunosuppressive environment for a variety of cancers." (PMID 38349866, 2024). "We confirmed for the first time that the expression of NUDT21 was significantly upregulated in HNSCC patient and in HHNSCC cells by PCR and pathological comparisons, which showed that NUDT21 was significantly increased in cancer tissues compared with adjacent normal tissues." (PMID 38349866, 2024). "Finally, we compared the differences in NUDT21 expression in cancer cell lines before and after cytokine treatment using the TISMO online tool." (PMID 38349866, 2024). "NUDT21 showed a significant positive correlation with methyltransferases in nearly all cancers." (PMID 38349866, 2024). "Therefore, a comprehensive analysis of NUDT21 in various cancers was conducted through pan-cancer research." (PMID 38349866, 2024). "Therefore, additional exploration of the relationship between NUDT21 and different pan-cancer immunosuppressive cells suggests that NUDT21 also plays a role in CAF, Tregs and MDSCs and suppresses anti-cancer immunity by targeting CTL." (PMID 38349866, 2024). "According to reports, NUDT21 has dual carcinogenic and inhibitory effects in cancer." (PMID 38349866, 2024). "Studying the expression of NUDT21 mediated APA process in cancers may become an attractive field, which will bring new markers for cancer diagnosis, prognosis and new therapeutic targets." (PMID 36816917, 2023). "For example, NUDT21 showed a dual role in different cancer types." (PMID 34594359, 2021). "Intriguingly, NUDT21 (CFIm25) showed a dual role in cancers." (PMID 34594359, 2021). "Interestingly, a study indicated that Nudt21, which is involved in polyadenylation of mRNAs, promotes differentiation of stem cells and cancer cells." (PMID 32979259, 2020). "In addition, identification of NUDT21-specific inhibitors can potentially advance the development of molecular-targeted therapeutics for various cancers like GBM." (PMID 29311812, 2017). "In addition, Tregs were negatively correlated with NUDT21 in a variety of cancers." (PMID 38349866, 2024). "Based on these findings, we propose that NUDT21 has the potential to serve as a diagnostic and prognostic biomarker for HHNSCC and could be targeted in future therapeutic interventions promoting personalized cancer treatment." (PMID 38349866, 2024). "However, there are some cancers where NUDT21 has the opposite effect." (PMID 36816917, 2023). "Pan-cancer results show that potential correlations of NUDT21 expression with TMB, MSI, DNA repair, RNA methylation, levels of immune infiltration, and various immune-related genes have been assessed in various cancers." (PMID 38349866, 2024). "In pan-cancer, HMGB1 had the highest positive correlation with NUDT21, followed by TLR4, CD276, and TNFRSF4." (PMID 38349866, 2024).
cancer (continued). "We found strong positive correlations between NUDT21 and M2 macrophages in HNSC, SKCM, TGCT, KIRC and LUSC, while NUDT21 was negatively correlated with CD8+ T and activated NK cells in many cancers." (PMID 38349866, 2024). "For example, NUDT21, the most important APA regulator favoring the long 3′UTR isoform, is lost in some types of cancer." (PMID 37737260, 2023). "Reduced levels of the CFI component NUDT21 have been reported to result in global 3′UTR shortening in a variety of disorders, particularly in cancers." (PMID 32560344, 2020). "By combining miRNA profiles with global APA site states in CRC patients, we found miRNAs appeared to regulate APA by modulating APA regulators such as NUDT21 and PABPN1, whereas APA regulated cancer-related gene expression by inducing 3'UTR alteration." (PMID 32153636, 2020). "Nudix Hydrolase 21 (NUDT21), an interacting partner of AGO2 and a key regulator of APA, is frequently downregulated in several cancers." (PMID 32276464, 2020). "In addition, we analyzed the NUDT21 and chemokine, receptor, and immune activator relationships, as shown in the heat map, NUDT21 was negatively correlated with several chemokines (CCL1, 2, 3, 4, and 5), numerous receptors, and immunostimulatory agents in pan-cancer." (PMID 38349866, 2024). "Therefore, it is not unexpected that NUDT21 depletion plays a central role in PH, a condition marked by fibrotic vascular stiffening and cancer-like hyperplasia of pulmonary arterial wall cells." (PMID 35671866, 2022). "The exact roles of NUDT21 in cancer incidence have not been elucidated." (PMID 29311812, 2017). "Currently, NF-κB-targeting cancer therapeutics have not been established and the NUDT21-driven NF-κB signaling axis might be a therapeutic target for MES GBMs." (PMID 29311812, 2017). "Four cancers (CHOL, KIOH, THYM, KIRP) showed a negative correlation of neoantigen with NUDT21 expression and a positive correlation with DLBC, SARC, GBM, and UCEC." (PMID 38349866, 2024). "The exact roles of NUDT21 in GBM and various other cancers have not been elucidated, thus more research is warranted." (PMID 29311812, 2017).
infection (7 papers, 2023 to 2026). The state of being infected such as from the introduction of a foreign agent such as serum, vaccine, antigenic substance or organism. "During infection, NUDT21 protein levels remained unchanged, and both western blotting and confocal microscopy showed no noticeable differences in its cellular distribution between infected and uninfected cells." (PMID 40384984, 2025). "In contrast, siRNA-mediated NUDT21 knockdown in BMDMs resulted in a significantly higher intracellular Mtb burden at 72 hours post-infection, underscoring the importance of NUDT21 in maintaining macrophage anti-Mtb function." (PMID 40384984, 2025). "Therefore, if the SAMBAR-Net prediction was correct, Nudt21 should be required for infection-induced B2 SINE ncRNA polyadenylation." (PMID 40768347, 2025). "Indeed, siRNA-mediated reduction of Nudt21 levels resulted in a decrease in B2 SINE ncRNA polyadenylation during MHV68 infection as compared to samples treated with control nontargeting siRNAs." (PMID 40768347, 2025).
NUDT21 also shares sentences with these, for which no sentence is quoted: lung carcinoma (5 papers); HIV-1 infection (4); idiopathic pulmonary fibrosis (2); lymph node metastasis (2); urothelial carcinoma of the bladder (2); acute kidney injury (1); atherosclerosis (1); autosomal dominant intellectual disability (1); chronic hepatitis (1); chronic lymphatic leukemia (1); Cirrhosis (1); coronary artery stenosis (1); coronary atherosclerosis (1); depression (1); diabetes (1); head and neck squamous cell carcinoma (1); Hypertension (1); inflammatory bowel disease (1); lung squamous cell carcinomas (1); mastitis (1); oculopharyngeal muscular dystrophy (1); preeclampsia (1); psoriasis (1); psychiatric disorder (1); rheumatoid arthritis (1); small cell lung carcinoma (1); steatosis (1); triple-negative breast carcinoma (1).